NES (nestin)
Diseases named in the same sentence as NES in open-access papers (continued):
Sharing a sentence is not in itself a finding about the gene and the disease.
pulmonary arterial hypertension (4 papers, 2016 to 2025). Pulmonary arterial hypertension (PAH) is a group of diseases characterized by mean pulmonary artery pressure >20 mmHg and elevated pulmonary arterial resistance leading to right heart failure. "On the other hand, vascular cells expressing nestin were implicated in the development of pulmonary hypertension." (PMID 27894297, 2016). "The goal of this study is to determine if Nestin expression contributes to endothelial proliferation in pulmonary arterial hypertension, using both lung tissues and endothelial cells." (PMID 30883593, 2019). "Likewise, in the chronic hypoxia/SU5416 animal model of pulmonary hypertension, Nestin+ endothelial cells were found in occlusive pulmonary vascular lesions." (PMID 30883593, 2019).
spinal cord injury (4 papers, 2014 to 2024). Penetrating and non-penetrating injuries to the spinal cord resulting from traumatic external forces (e.g., WOUNDS, GUNSHOT; WHIPLASH INJURIES; etc.). "A pool of endogenous neural progenitor cells (NPCs) found in the ependymal layer and the sub-ependymal area of the spinal cord are reported to upregulate Nestin in response to traumatic spinal cord injury (SCI)." (PMID 27013972, 2016). "Recent studies have found that nestin+ leptomeningeal-derived neural progenitor cells (NPCs) were identified from this nonconventional neurogenic region of adult leptomeningeal cells following cortical infarction and spinal cord injury 5, 7-9." (PMID 31588228, 2019).
Tremor (4 papers, 2015 to 2021). An unintentional, oscillating to-and-fro muscle movement about a joint axis. "Nestin-Cre; Shox2flox/− mutant pups also displayed tremors 16–26 h following birth, which could be related to defects in neural circuitry or result from a loss of Shox2 function in other regions of the hindbrain." (PMID 26156498, 2015).
amyloid (3 papers, 2012 to 2022). "In a recent study of amyloid-induced inflammatory responses in the rat retina, induced inflammatory responses were characterized by increases in markers for microglia and astrocytes (ionized calcium-binding adaptor molecule 1 (Iba-1), GFAP and nestin)." (PMID 23819902, 2013). "Reactive gliosis as a result of different experimental brain injuries induces the re-expression of nestin, but we here report that this does not happen in the context of amyloid-induced gliosis in the APPswePS1dE9 mice." (PMID 22912745, 2012). "We found a reduction in the numbers of Nestin-, Vimentin-, Nestin/Vimentin-, and Sox 2-positive cells in the olfactory bulb, hippocampus, and SVZ after amyloid exposure, although in some cases, the reduction was not significant." (PMID 36499771, 2022).
bladder cancer (3 papers, 2020 to 2023). "Nestin, a class VI intermediate filament protein, is also an independent predictor of cancer-specific survival after radical cystectomy in bladder cancer patients." (PMID 31892978, 2020). "The high expression of ABCB9, SPTBN2, GULP1, IGF1, P4HB, NES and DPYSL2 and the low expression of ANXA6, OAS1, RAD9a, DNASE2B and FANCF would be beneficial to the prognosis of bladder cancer patients." (PMID 37845668, 2023).
cholangiocarcinoma (3 papers, 2018 to 2023). A carcinoma that arises from the intrahepatic biliary tree (intrahepatic cholangiocarcinoma) or from the junction, or adjacent to the junction, of the right and left hepatic ducts (hilar cholangiocarcinoma). "Nestin has recently been found to be highly expressed in intermediate cells of cHCC-CCA, cholangiocellular-differentiated areas of cHCC-CCA as well as cholangiocarcinomas." (PMID 36672443, 2023).
cutaneous melanoma (3 papers, 2012 to 2024). A primary melanoma arising from atypical melanocytes in the skin. "Phosphorylated serine residues have been reported in Nestin protein from the brain of mouse embryos and mouse skin melanoma and have been assumed by similar data in human HeLa cells." (PMID 23028390, 2012). "The differential expression analyses perfomed using GEPIA2 revealed a significantly higher mRNA expression level for LOXL3 and NES in cutaneous melanomas, both with and without confirmed BRAF mutations, compared to normal skin samples." (PMID 39273022, 2024).
Dyskinesia (3 papers, 2018 to 2023). A movement disorder which consists of effects including diminished voluntary movements and the presence of involuntary movements. "Interestingly, in rat models following chronic exposure with Levodopa, VEGF expression, angiogenesis, and proliferating micro vessels stained by nestin were more prominent in animals with dyskinesia." (PMID 31824400, 2019). "Heat-induced dyskinesia also occurred consistently in Nestin-Cre;Prrt2−/− mice." (PMID 29056747, 2018).
esophageal cancer (3 papers, 2014 to 2018). A primary or metastatic malignant neoplasm involving the esophagus. "It has been shown that nestin is highly expressed in esophageal carcinoma and that there is a strong association of nestin expression with poor prognosis in esophageal carcinoma patients." (PMID 29029411, 2017). "Because no previous studies have provided detailed information on signaling mechanisms involved in the proliferation of esophageal cancer cells relevant to the nestin phenotype, we further investigated the mechanism underlying this linkage." (PMID 24966803, 2014). "Nestin was further investigated as it was found to correlate with decreased overall survival in patients with oesophageal cancer when using the in silico microarray meta-analysis tool PrognoScan, suggesting its important role in OAC biology." (PMID 29593339, 2018). "In this study, we demonstrated that the expression level of nestin was correlated the invasiveness of esophageal carcinoma and inhibition of nestin enhanced paclitaxel sensitivity to apoptosis of esophageal carcinoma cells." (PMID 29029411, 2017). "To investigate the effect of nestin on apoptosis in esophageal carcinoma cells, we used nestin siRNA to inhibit nestin expression in Eca-109 cells." (PMID 29029411, 2017). "To examine the expression of nestin in esophageal carcinoma, we used in situ hybridization to detect nestin mRNA level." (PMID 29029411, 2017). "In the present study, we sought to characterize the nestin phenotype in ESCC of Chinese population and assess its association with esophageal cancer cell proliferative properties and clinical prognosis and pathological parameters." (PMID 24966803, 2014). "To further elucidate whether nestin inhibition could enhance paclitaxel sensitivity to esophageal carcinoma cells, we applied nestin siRNA in esophageal squamous cell carcinoma Eca-109 cells." (PMID 29029411, 2017). "The highest expression of nestin was observed in invasive esophageal carcinoma." (PMID 29029411, 2017). "Flow cytometry and TUNEL staining both showed that combination of paclitaxel treatment and nestin knockdown resulted in greater induction of apoptosis of esophageal carcinoma cells as compared with the cells transfected with control siRNA (also treated with paclitaxel)." (PMID 29029411, 2017). "Recently, nestin has also been detected in esophageal carcinoma." (PMID 29029411, 2017). "However, there has been little research on the relations between nestin expression and the therapeutic efficacy of paclitaxel in the esophageal carcinoma in the past years." (PMID 29029411, 2017). "Our study offers convincing evidence that treatment with paclitaxel combined with nestin inhibition may improve chemosensitivity of patients with esophageal carcinoma." (PMID 29029411, 2017). "Targeted regulation of nestin may thus have therapeutic applications in the treatment of human esophageal cancer." (PMID 24966803, 2014). "Collectively, our data suggest that tumor cells expressing nestin promote ESCC cell proliferation and apoptosis, which may constitute a key mechanism of nestin-mediated metastasis in esophageal cancer cells." (PMID 24966803, 2014). "However, the specific function of nestin positive tumor cells in the invasive and metastatic behaviors of esophageal cancer remains unclear." (PMID 24966803, 2014). "To explore the different expression of nestin in non-metastasized esophageal carcinoma and metastasized esophageal carcinoma, we did nestin immunohistochemistry staining." (PMID 29029411, 2017).
esophageal squamous cell carcinoma (3 papers, 2014 to 2022). Esophageal squamous cell carcinoma (ESCC) is a type of esophageal carcinoma (EC) that can affect any part of the esophagus, but is usually located in the upper or middle third. "The stem cell-associated intermediate filament nestin has recently been linked with neoplastic transformation, but the specific mechanism by which nestin positive tumor cells leads to malignant invasion and metastasis behaviors of esophageal squamous cell carcinoma (ESCC) remains unclear." (PMID 24966803, 2014).
HCMV infection (3 papers, 2013 to 2023). "The detection of HCMV-infected cells expressing nestin in all brain regions, also in areas where this marker was scarcely present, may suggest that HCMV infection could interfere with neuronal differentiation." (PMID 35933637, 2023). "While expression of the NSPC markers Sox2 and Pax6 were kept at high levels following HCMV infection, that of another NSPC marker Nestin was markedly suppressed at 7 dpi." (PMID 24144363, 2013).
liver fibrosis (3 papers, 2023 to 2026). "For example, AAV-mediated silencing of CD47, KDM4D and nestin has been used as a strategy to reduce liver fibrosis." (PMID 38267432, 2024).
mesenchymal tumors (3 papers, 2017 to 2020). "All the PIWIL2-GFP fibroblasts derived tumors tested stained positive for the transfected gene, PIWIL2, as well as VIMENTIN (marker of mesenchymal tumors), Synaptophysin (SYN, markers of neurogenic tumors) and NESTIN." (PMID 28103575, 2017).
migraine (3 papers, 2022 to 2025). "Both male and female nestin/hRAMP1 mice showed significant migraine-like behavior when compared to control littermates." (PMID 40708951, 2025). "They studied light aversive behavior in migraine by using a transgenic mouse line (nestin/hRAMP1), which upregulates the receptor protein RAMP1, a subunit of the CGRP receptor required for CGRP binding." (PMID 40708951, 2025). "This study suggests that the hypersensitive nestin/hRAMP1 mouse may serve as a model for difficult to treat cases of migraine that exhibit increased motion sensitivity." (PMID 39652533, 2024). "The nestin/hRAMP1 mouse model has been extensively studied to manipulate CGRP’s effects, simulate migraine-like surrogate behaviors, and assess the efficacy of migraine drugs." (PMID 39652533, 2024). "The migraine animal model also induces an increase in circulating CGRP levels in plasma and cerebrospinal fluid of the nestin/hRAMP1 transgenic mice." (PMID 35784726, 2022). "Results from migraine blocker experiments were challenging to interpret, but the data suggests that olcegepant is incapable of reversing CGRP-induced or endogenous alterations in the nestin/hRAMP1 mice, while rizatriptan was ineffective in both the nestin/hRAMP1 and control mice." (PMID 39652533, 2024).
Parkinson disease (3 papers, 2011 to 2022). A progressive degenerative disorder of the central nervous system characterized by loss of dopamine producing neurons in the substantia nigra and the presence of Lewy bodies in the substantia nigra and locus coeruleus. "The number of SOX-2- and nestin-expressing cells is also reported to be reduced in the dentate gyrus of Parkinson’s disease patients with dementia." (PMID 31980673, 2020). "In this case, nestin-positive precursors, expanded inbFGF (basic fibroblast growth factor), differentiated into tyrosinehydroxylase-positive neurons that secreted dopamine and were functional bybehavioral tests when grafted into a rat model for Parkinson's disease." (PMID 21533199, 2011).
rhabdomyosarcoma (3 papers, 2008 to 2024). A rare aggressive malignant mesenchymal neoplasm arising from skeletal muscle. "In a study, where Nestin expression was evaluated immunohistochemically in cases of nephroma, rhabdomyosarcoma, NB, rhabdoid tumor, and desmoplastic small round cell tumor, it was shown to be largely positive." (PMID 38925618, 2024). "However, there is only a minimum of similar findings in soft tissue sarcomas; the only one evidence of nestin was given in pediatric rhabdomyosarcomas and angiosarcomas." (PMID 18925963, 2008).
vascular tumors (3 papers, 2013 to 2025). "Therefore, we should continue to observe and analyze the assisted diagnostic value of nestin in malignant vascular tumors in the future." (PMID 23420140, 2013). "Nestin expression is also observed in the endothelial cells of adult tissues that replenish by angiogenesis and in the endothelium of vascular neoplasms and cancers, suggesting that nestin is a marker for angiogenesis." (PMID 31675305, 2019). "The result showed positive expression of nestin in the cytoplasm and we found that the expression of nestin in malignant vascular tumors was related to the shape change of the tumor." (PMID 23420140, 2013). "Therefore, we compared nestin expression in endothelial cells of haemangiomas and lymphangiomas, which are benign vascular tumors of different origins." (PMID 40149541, 2025).
ameloblastoma (2 papers, 2021 to 2024). The most common odontogenic tumor, arising from the epithelial component of the embryonic tooth and usually affecting the molar-ramus region of the mandible or maxilla. "While there is limited documentation on nestin expression in odontogenic neoplasms or related lesions, it has been observed that all ameloblastomas and malignant ameloblastomas exhibit negativity for nestin." (PMID 38390958, 2024). "The expression of nestin in ameloblastomas and malignant ameloblastomas has been reported in the literature to be negative." (PMID 33917771, 2021). "Our results suggest nestin expression to be an indicator for ameloblastic carcinoma, and CD138 and alpha-SMA to be promising biomarkers for the malignant transformation of ameloblastoma." (PMID 33917771, 2021). "The main aim of this study was to explore the immunoexpression of stem cell markers nestin, CD138 (syndecan-1), and alpha-SMA in a series of four cases of ameloblastic carcinoma and to compare this data to an ameloblastoma immunoexpression profile." (PMID 33917771, 2021). "Nestin was observed in one ameloblastic carcinoma stroma sample, whilst CD138 was positive in one ameloblastoma case, one desmoplastic ameloblastoma case, and in two ameloblastic carcinoma stroma samples." (PMID 33917771, 2021).
ampullary adenocarcinoma (2 papers, 2015 to 2016). "In ampullary adenocarcinoma, over expression of nestin/CDK5 was involved in several oncogenic pathways (the activation of NOTCH, TGF-β1, or PDGFR pathways) that facilitated invasiveness of cancer." (PMID 26860827, 2016). "The findings in the present study suggest that nestin plays various roles in early and in advanced ampullary adenocarcinoma." (PMID 25371063, 2015). "This study assessed the functions of nestin in ampullary adenocarcinoma and its correlation with clinical outcomes of patients." (PMID 25371063, 2015). "The activation of multiple oncogenic pathways, combined with the stemness characteristics of nestin, formed a complex network in advanced ampullary adenocarcinoma." (PMID 25371063, 2015). "Immunohistochemistry (IHC), reverse transcription-polymerase chain reaction, and cDNA microarray of nestin in ampullary adenocarcinoma was compared with normal duodenum." (PMID 25371063, 2015). "The varying behaviors of CDK5 may explain why nestin plays various roles in early and in advanced ampullary adenocarcinoma." (PMID 25371063, 2015). "Inhibition of nestin in the select patients with ampullary adenocarcinoma could provide a therapeutic solution." (PMID 25371063, 2015). "We speculate that nestin exhibits various functions in the early and advanced stages of ampullary adenocarcinoma." (PMID 25371063, 2015). "This may be the reason that patients with weak nestin expression in ampullary adenocarcinoma had a favorable prognosis after undergoing radical resection." (PMID 25371063, 2015). "We studied the function of nestin in ampullary adenocarcinoma." (PMID 25371063, 2015). "Inhibiting nestin in patients who exhibit nestin-overexpressed ampullary adenocarcinoma may be a method of preventing cancer recurrence." (PMID 25371063, 2015). "Our study demonstrated that nestin performs a dual role in ampullary adenocarcinoma." (PMID 25371063, 2015). "The reciprocal expression of nestin and RAC1 were explored using a cDNA microarray analysis in the early stages of ampullary adenocarcinoma." (PMID 25371063, 2015). "Nestin expression was upregulated in the early and locally advanced stages of ampullary adenocarcinoma, but was not upregulated in the intermediate stage." (PMID 25371063, 2015).
Anorexia (2 papers, 2008 to 2016). Lack of desire to eat (loss of appetite). "Additionally, anorexia increased the expression of the intermediate filaments vimentin and nestin." (PMID 27579183, 2016). "Accordingly, GFAP+ cells deficit may be replaced by vimentin+/nestin+ cells in anorexia." (PMID 27579183, 2016). "We conclude that anorexia reduces the hippocampal GFAP+ cell density and increases vimentin and nestin expression." (PMID 27579183, 2016). "Acute i3vt GM-CSF treatment restored the hypothalamic expression of OX to normal levels in Stat5fl/fl; Nestin-Cre mice, however, suggesting that STAT5 mediates GM-CSF-induced anorexia by OX-independent mechanisms, and that GM-CSF can regulate OX mRNA expression independently of STAT5." (PMID 18286195, 2008).
astrocytic tumor (2 papers, 2015 to 2020). A glial tumor of the brain or spinal cord showing astrocytic differentiation. "CD133 and Nestin present as potential biomarkers for advanced pathological grade and poor survival in patients with astrocytic tumor." (PMID 31677196, 2020). "The expressions of CD133 and Nestin in astrocytic tumor tissues were analyzed by immunohistochemistry assay." (PMID 31677196, 2020). "Nestin has also been proposed as a useful marker for examining the infiltration of malignant astrocytic tumors cells into the surrounding tissue." (PMID 25940437, 2015). "We disclosed that CD133 and Nestin both predicted poor OS in patients with astrocytic tumor." (PMID 31677196, 2020). "Therefore, in this study, we evaluated the interaction between CD133 and Nestin and further assessed the correlation of CD133 and Nestin with clinicopathological characteristics and survival in patients with astrocytic tumor." (PMID 31677196, 2020). "In conclusion, CD133 and Nestin are correlated with advanced WHO grade and poor survival in patients with astrocytic tumor, which benefits the exploration of prognostic factor for astrocytic tumor." (PMID 31677196, 2020). "We aimed to investigate the interaction between CD133 and Nestin and further assessed the correlation of CD133 and Nestin with clinicopathological characteristics and survival in patients with astrocytic tumor." (PMID 31677196, 2020). "In order to determine the interaction between CD133 and Nestin, Spearman's rank correlation test was performed, which observed that CD133 expression was positively correlated with Nestin expression in astrocytic tumor tissue (P < .001, r = .299)." (PMID 31677196, 2020). "Thus, we recruited a larger number of patients with astrocytic tumor, and our study reported that CD133 and Nestin expressions were both correlated with advanced WHO grade but not with age or gender in patients with astrocytic tumor." (PMID 31677196, 2020). "Although CD133 and Nestin were shown to be correlated with advanced WHO grade and poor survival in our study, the detailed mechanisms of CD133 and Nestin in regulating cell stemness and tumor progression in astrocytic tumor were not investigated." (PMID 31677196, 2020).